SPARC (secreted protein acidic and cysteine rich)
Diseases named in the same sentence as SPARC in open-access papers (continued):
Sharing a sentence is not in itself a finding about the gene and the disease.
cancer (continued). "Through literature search and analysis of clinical cancer samples, it is found that SPARC is located in the nucleus and cytoplasm of ESCC and SPARC can be considered as a prognostic indicator." (PMID 37577749, 2023). "The SPARC gene is also involved in the epithelial-mesenchymal transition (EMT) process, which is a critical phenomenon leading to a more aggressive cancer cell phenotype." (PMID 37509139, 2023). "The study identified FN1, CD44, TIMP1, SPARC and SNAI2 as common coding hub proteins for most of the drug-resistant cancer types." (PMID 35534592, 2022). "Summary of top four selected genes (COL5A2, ITGAV, SPARC and ACTA2) which were correlated with EMT signature in 32 pan cancer cohorts was presented in radar graphs, and the well-known CDH1 (Epithelial) and VIM (Mesenchymal) genes were included as controls." (PMID 35046456, 2022). "Over recent years, SPARC member SMOC2 was studied for its role in development and fibrosis, suggesting a possible function for this protein in cancer progression since these tissue-altering processes share key signaling pathways." (PMID 35869056, 2022). "Although the SPARC and VIM genes had higher expression rates in GBM, they were found high in other cancer types." (PMID 35571016, 2022). "Even in the case of the promoters of the CXCL12, FAP, and SPARC genes, which showed high transcription levels in IVP-9TS as compared to cancer cell lines." (PMID 33804861, 2021). "SPARC expression was positively and significantly correlated to CD276 (B7-H3) in all the eight cancer types." (PMID 33240930, 2020). "A collation of 73 TEC marker genes from five studies showed that at most, only two cancer types shared one of these five genes (EGFL6, HEYL, MMP9, SPARC, PLXDC1), and the rest were expressed uniquely in only one cancer." (PMID 32375250, 2020). "Comparison of the expression level in AEM with the expression level in advanced carcinoma showed that the difference in expression was statistically significant for SPARC and SPON2 (p < 0.001 for SPARC and p = 0.001 for SPON2)." (PMID 33322258, 2020). "Cancer accounts for only 3.3% of total diseases related to selected myokines (apelin, BDNF, IL-15, irisin, SPARC), but additional myokines have been shown to be more clearly involved in cancer cachexia." (PMID 30984014, 2019). "Overexpression of SPARC disrupts the recognition of VEGF by its receptor, inhibits the activation of ERK1/2, and consequently limits the proliferation of cancer cells." (PMID 31139014, 2019). "Four of the genes (RARβ2, SPARC, CDH13, CYB5R2) showed significantly higher methylation in the cancer cases when compared with the control cases (p<0.05)." (PMID 30204798, 2018). "Studies have shown that SPARC expression in mesenchymal and stromal cells (MSC) was significantly higher compared to expression in cancer cells and in normal mucosa tissues." (PMID 30175151, 2018). "In conclusion, SPARC regulates the fibrillar ECM deposition of TGFBI through a novel interaction, subsequently influencing cancer cell behavior." (PMID 27622658, 2016). "Whereas all of the assessed genes showed high expression in fibroblasts, several genes, including SPARC, ADAM12, TIMP2, MMP2, and COL5A2 were also expressed in carcinoma cells, albeit at lower levels." (PMID 27128408, 2016). "SPARC, RECK, TNFAIP3 and CXCL14 were down-regulated (p < 0.05) in BCBM as compared to primary BC samples irrespectively of the cancer subtype, while for CADM1, this correlation was found in HR positive and TNBC samples." (PMID 24833255, 2014). "SPARC also influences the secretion and activation of several MMPs, including MMP-1, -2, and -7, to promote cancer invasiveness." (PMID 22481923, 2012). "Indeed, SPARC is required for the correct assembly of the collagen meshwork that provides adhesive substrate to cancer cells, yet, it might also inhibit integrin-mediated adhesion and the generation of signals stemming from the integrin-linked kinase activation." (PMID 22400028, 2012).
cancer (continued). "Secreted protein acidic and rich in cysteine (SPARC), a matricellular glycoprotein, modulates cellular interaction with the extracellular matrix and is capable of altering the growth of various cancers." (PMID 20087345, 2010). "However, research in this area is still in early stages, targeting MMP9, SPARC and ITGA5 in OSF has the potential to prevent altered ECM remodelling and its contribution to both fibrosis and its progression to cancer." (PMID 39865173, 2025). "We analyzed expression levels and intracellular localization of seven common cancer antigens, CLDN1, EphB4, LAT1, FOXM1, HSP105α, ROBO1, and SPARC, and human leukocyte antigen (HLA) class I via immunohistochemical staining of 85 surgical specimens from primaries and liver metastases." (PMID 40806530, 2025). "The INTERVAL-GAP4 trial found increased serum levels of the myokines secreted protein acidic and rich in cysteine (SPARC) and oncostatin M (OSM) after 6 months of combined RT and AT, suggesting that these may play a role in exercise-induced cancer suppression." (PMID 39766184, 2024). "However, denatured albumin has a diminished ability to bind to GP60 or SPARC, so how to maximize the preservation of albumin activity is the key to the effective use of GP60 or SPARC for cancer therapy." (PMID 38323081, 2024). "Moreover, SPARC activation of the ERK and AKT downstream signaling pathways modulates cancer cell adhesion, motility and invasion." (PMID 36346290, 2023). "SPOCK1 (SPARC/osteonectin, cwcv and kazal-like domains proteoglycan 1), also referred to as testincan-1, is a crucial regulator of the dynamic balance of extracellular matrix (ECM) and mediates epithelial-to-mesenchymal transition (EMT) in cancer cells." (PMID 35433415, 2022). "It is worth highlighting that increased SPARC expression has been reported in negative biological status such as metabolic disorders, rheumatoid arthritis, cancer, coronary artery disease and intracranial aneurysms." (PMID 35741776, 2022). "Secreted protein acidic and rich in cysteine (SPARC), also known as osteonectin or basement membrane 40 (BM40), is the central receptor contributing to the entrapment and catabolism of albumin inside the cancer cell." (PMID 35456562, 2022). "Incorporation of SPARC-integrin-FN1-mediated activation of AKT may be involved in activation of fibroblasts and dominant changes in ECM to help cancer cells to mobilize or invade into adjacent stroma." (PMID 33579227, 2021). "Interestingly, several genes were known to be regulated by the TGFβ pathway (e.g., BMF, COL4A4) and/or expressed in several cancers (e.g., HOTAIR, MRC2, POSTN, SPARC)." (PMID 34830779, 2021). "In conclusion, our study indicated that SPARC induced AKT phosphorylation and EMT in cancer cells." (PMID 33579227, 2021). "After transportation into the tumor interstitium via the caveolae-mediated pathway, nab-PTX could bind to SPARC, facilitating the release of PTX around cancer tissues and improving the anticancer effects." (PMID 33855017, 2021). "Understanding which cancers may likely benefit from HSP27 inhibition therapy by proxy of the relevant biomarkers (such as COL11A1, SPARC, and potentially type I collagen) may lead to more treatment successes." (PMID 34638339, 2021). "Moreover, SPARC, SERPINE1, and THBS1 are reported in the Wikipathways 2019 human database to play a role senescence and autophagy in cancer." (PMID 34064977, 2021). "The CTGF, IGFBP2, JAG1, and SPARC promoters can provide higher transgene expression in fibroblasts than in cancer cells, but the nonspecific viral promoters CMV, SV40, and the recently studied universal PCNA promoter have the same features." (PMID 33804861, 2021). "Correlations between the expression level of BGLAP, SPARC, and SPP1 in different cancer types." (PMID 33240930, 2020).
cancer (continued). "It has been realized that the permeability of vessels and cancer metastasis can be advanced by multiple factors released from cancer cells, such as vascular endothelial growth factor (VEGF) and secreted protein acidic and cysteine-rich (SPARC)." (PMID 32756339, 2020). "Moreover, as the phenotype of EMT is correlated with the metastasis of cancers, two EMT biomarkers, E-cadherin and Vimentin were detected in ESCC cells transfected with SPARC siRNAs using western blotting." (PMID 31897236, 2020). "Particularly, SPARC and SPP1 expression were positively correlated to DC-related markers CD86, NRP1, and inhibitory checkpoint markers including LAIR1, HAVCR2, and PDCDLG2 in most cancer types." (PMID 33240930, 2020). "Additionally, SPARC regulates angiogenesis by sequestering VEGF, thus restricting the activation of VEGF receptor and ERK1/2, consequently limiting the proliferation of cancer cells." (PMID 32226513, 2020). "Combined analysis of SPARC from heterogeneous sources revealed that the Cancer−/GCAF+ group had the best prognosis among the groups; the difference in OS between this group and the Cancer−/GCAFs− group was statistically significant (χ2 = 7.071, P = 0.008)." (PMID 31139014, 2019). "SPARC mRNA was expressed by all fibroblast populations isolated, while expression in the used cancer cells was extremely low or absent." (PMID 31554208, 2019). "Decreased expression of VEGF and MMP-9 in medulloblastoma cells that overexpress osteonectin, also referred to as Secreted Protein Acidic and Rich in Cysteine (SPARC), leads to decreased angiogenesis and tumor growth, indicating the pro-angiogenic role of MMP-9 in cancer tissues." (PMID 31921634, 2019). "We found significant and direct correlation of PSA and RARβ2 methylation (p = 0.00036; r = 0.296) and SPARC methylation (p = 0.0134; r = 0.202) in the non-cancerous control but not the cancer cases." (PMID 30204798, 2018). "Recent studies suggest a relationship between SPARC and EMT program in highly metastatic cancers." (PMID 28969021, 2017). "In addition, the CTC population showed enriched expression of cancer stem cell (CSC) markers and the extracellular matrix (ECM) protein, SPARC." (PMID 28569190, 2017). "The expression of SPARC was high in all isolated CTCs and cancer cell-line cells analysed, and it was nearly absent in leucocytes." (PMID 28569190, 2017). "Since SPARC regulates TGFBI deposition in the ECM, we determined how the Met5A-derived ECM could influence cancer cell motility and response to paclitaxel." (PMID 27622658, 2016). "In addition, it has been suggested that SPARC secreted by macrophages increases cancer cell migration and metastasis in an integrin-dependent manner, consistent with our own results, thus SPARC may also influence cancer dissemination in a TGFBI-dependent manner." (PMID 27622658, 2016). "Although a crucial factor in promoting cancer metastasis and invasion, the mechanism(s) by which increased SPARC expression enhances invasive ability in vivo is not understood." (PMID 26926673, 2016). "Altogether, the early identification of SPARC/Endothelin 1/ETAR in dysplastic lesions would be important to devise therapies preventing metastasis engraftment, since often carcinoma cells spread to distant organs at the time or even before patients present with cancer." (PMID 26703564, 2015). "The expression of SPARC is varied in different types of cancers, and its role in tumorigenesis appears complex and is not well defined." (PMID 24535175, 2014). "SPARC, through its inherent involvement in directing ECM deposition, cell-ECM interactions and growth factor signaling, plays numerous roles in regulating the multiple hallmarks of cancer including angiogenesis, migration, proliferation and survival." (PMID 23123816, 2013).
cancer (continued). "Among the ten genes, five of the TSGs (ATM, APC, BRCA2, NF1, and PTEN) were annotated with positive effects on apoptosis; the other three TSGs (PEG3, SPARC, and RPS6KA2) were also reported to increase apoptosis in sporadic epithelial OVC or other types of cancer." (PMID 22952919, 2012). "SPARC expression was absent in most of the cancer cells, but instead present at high levels in the peritumoural tissue harbouring fibroblasts and pancreatic stellate cells (PSCs)." (PMID 19920824, 2010). "SPARC can modulate ERK activation by activating a G-protein coupled receptor, converging on the integrin signaling pathway, as well as EphA2 receptor known for its importance in cancer development and its ability to converge on integrin signaling." (PMID 20955590, 2010). "The transcriptional regulation of the SPARC gene expression has not been fully elucidated and the effects of anti-cancer drugs on this process have not been explored." (PMID 20687958, 2010). "Ad-wt exhibited CPE on almost every cancer cell line at a low titer of 5×104 (MOI of 1) to 5×106 vp/ml (MOI of 100) regardless of SPARC expression levels." (PMID 19337591, 2009). "The expression of SPARC is variable in different cancers, and its role in tumorigenesis appears complex and not well defined." (PMID 18458674, 2008). "In addition, this panel includes ECM components that stimulate cancer cell invasion, such as collagens (e.g., COL1A1, COL4A1), the extracellular matrix glycoproteins laminins (e.g., LAMA1, LAMC1), fibronectin (FN1), and SPARC, among others." (PMID 38437557, 2024). "In essence, while HDACs are known for their diverse gene regulatory roles and implications in both cancer and non-cancerous diseases, their specific influence on SPARC expression, particularly in the cancer landscape, remains unknown." (PMID 38650694, 2024). "Importantly, SPARC was previously reported to be ectopically expressed in the stroma of digestive tumors but not by cancer cells themselves." (PMID 36831450, 2023). "In addition to modulation of extracellular matrix, SPARC also regulates cell adhesion, proliferation, survival, apoptosis, migration, invasion, and induction of epithelial-to-mesenchymal transition (EMT) in cancer cells." (PMID 33579227, 2021). "Secreted Protein Acidic and Rich in Cysteine (SPARC)-related modular calcium-binding protein-2 (SMOC2), a secreted matricellular protein, is reported to be involved in various processes related to cancer progression such as regulating the cell cycle, angiogenesis, and invasion." (PMID 32184420, 2020). "However, we observed an opposite expression in AT compared to cancer cells, suggesting a different role of this lncRNA in visceral adipocytes, that could potentially involve H19 target genes STAT3 and SPARC." (PMID 32714872, 2020). "However, cancer cell-derived SPARC was not statistically correlated with OS based on the log-rank test (χ2 = 1.055, P = 0.304)." (PMID 31139014, 2019). "No SPARC-induced alterations have yet been found in the cancer cells that may explain the increased invasiveness." (PMID 31554208, 2019). "In addition, SPARC is not directly implicated in the cellular transformation and cancer initiation as spontaneous cancers do not develop in mice with germline deletion of SPARC." (PMID 27564266, 2016). "Moreover, our analysis indicates that LOX is likely co-expressed with MMP2, COL1A1 and SPARC, all of which contribute to initiating cancer metastasis and EMT, and that bisphosphonates inhibit MMP2 activity, COL1A1-driven osteoporotic fracture and SPARC-stimulated EMT." (PMID 27147578, 2016). "This switch from a predominantly proliferative phenotype in low-grade cancer to an invasive phenotype in higher-grades may explain why genes (COL1A2 and SPARC) coding for extracellular matrix (ECM) proteins are independently upregulated in higher-grade stroma but not in low-grade stroma." (PMID 27152194, 2016).
cancer (continued). "SPARC belongs to the matricellular group of proteins, which are transiently secreted to the Extracellular matrix (ECM), without becoming part of the ECM mesh; mediating the adhesion between carcinoma cell surface and ECM, SPARC influences the epithelial-mesenchymal transition (EMT)." (PMID 27187355, 2016). "In dysplasia adjacent to carcinoma and in pair-matched specimens of bone metastasis we examined SPARC expression and localization as well as Endothelin 1/ETAR signals by immunohistochemistry, and the evaluation of plasma levels of SPARC by ELISA was also performed." (PMID 26703564, 2015). "Although there is growing evidence for an important role for SPARC in a variety of cancers, there is no unifying model, which explains all facets of its function and contribution to the development and progression of cancer." (PMID 22879971, 2012). "For example, in some solid cancers, conspicuous SPARC expression by neoplastic and stromal cells can either promote epithelial-to-mesenchymal transition (EMT), and favour tissue invasion and metastasis, or exercise an antiproliferative effect on neoplastic cells, thus limiting cancer progression." (PMID 22400028, 2012). "However, the SPARC protein does not contain a RGD sequence; thus, the SPARC-induced motility of cancer cells likely involves an indirect mechanism." (PMID 22481923, 2012). "Recent studies investigating SPARC expression in human pancreatic tissues reported high levels of SPARC in the surrounding stromal tissue harbouring fibroblasts and PSCs, whereas SPARC was often absent in the cancer cells." (PMID 19920824, 2010). "So it could be seen in most ESCC that SPARC was prominently expressed by stromal fibroblasts in a background of negative cancer cell reactivity." (PMID 17187659, 2006). "In exploring the mechanism behind the enhanced cancer cellular uptake of the prepared conjugates, we thought that the native receptors of the proteins may play very limited roles, as albumin and RBD bind to different receptors (e.g., SPARC/gp60 for albumin and ACE2 for RBD)." (PMID 36684090, 2023). "Finally, if demonstrated that SPARC methylation can be detected in cfDNA of NSCLC, it could represent an interesting non-invasive marker of early diagnosis of NSCLC to test in liquid biopsy or to monitoring cancer evolution in NSCLC patients." (PMID 32580473, 2020). "We also observed a direct correlation between methylation of RARβ2 (p = 0.0036; r = 0.293) and SPARC (p = 0.0134; r = 0.20) loci with PSA level in the controls but not the cancer cases." (PMID 30204798, 2018). "Among other highly expressed genes in SPFs without CCCM stimulation, we found POSN, SPARC, or COL4A1, which are known to be highly expressed in the cancer stroma; and many of these are prognostic factors." (PMID 24505356, 2014). "Intra-tumoral fibroblast cells scored SPARC- and Collagen VI-positive in ECM3 and in the majority of non-ECM3 carcinomas." (PMID 23441215, 2013). "SPOCK1, a secreted matricellular protein and also called SPARC, is a critical regulator of EMT induction and could be a novel therapeutic target for cancer progression." (PMID 35360859, 2022). "However, in previous studies, SPARC/SPP1/BGLAP was deemed independent functional molecule rather than marker of osteomimicry, and was investigated separately in different cancer types and no one had combined these molecules and explored their prognostic value in pan-cancer analyses." (PMID 33240930, 2020). "Interestingly, cancer exosomes, but not normal exosomes, modulated expression of matrix remodelling (EFEMP1, DDK3, SPARC), cell cycle (EEF2K), membrane remodelling (LAMP2, SRPX), differentiation (SPRR2E), apoptosis (CTSC), transcription/translation (KLF6, PUS7)." (PMID 30008265, 2018).